HK2 (hexokinase 2)
Diseases named in the same sentence as HK2 in open-access papers (continued):
Sharing a sentence is not in itself a finding about the gene and the disease.
colon carcinoma (continued). "Furthermore, our results indicate that miR-143 mediated down-regulation of HK2 affects glucose metabolism in colon cancer cells." (PMID 22691140, 2012). "Hence, the transcriptional factor c-Myc may directly bind to transcriptional promoter region of HK2, rendering a metabolic shift toward glycolysis in colon cancer cells." (PMID 28445985, 2017). "As PHLPP is lost in a majority of colon cancer patients and PHLPP loss renders cancer cells sensitive to glucose restriction-induced cell death, selectively targeting HK2 (such as using agents that dissociate HK2 from mitochondria) may provide a novel treatment option for colon cancer patients." (PMID 28179998, 2017). "In addition, we analyzed the nature of the endogenous PHLPP–Akt–HK2 complex in colon cancer cells." (PMID 28179998, 2017). "Importantly, our findings that PHLPP loss induced upregulation of glycolysis can be abolished by inhibition of Akt, dissociation of HK2 from the mitochondria or knockdown of HK2 indicate that PHLPP regulates glucose metabolism through a PHLPP/Akt/HK2 axis in colon cancer cells." (PMID 28179998, 2017). "In colon cancer, it has been demonstrated that AKT2 can interact with and phosphorylate hexokinase 2 (HK2), the rate-limiting enzyme in glycolysis." (PMID 38396845, 2024). "Matrine has been found in studies to drastically suppress the expression of HIF-1α and its downstream regulatory targets of glucose metabolism GLUT1, HK2 and LDHA in colon cancer HCT116 and SW620 cells, reversing the Warburg Effect." (PMID 36339566, 2022). "In colon cancer cases, a positive correlation between SPIB and HK2 expression was noted (R = 0.1441, p < 1 × 10−4) or PGK1 (R = 0.3072, p < 1 × 10−4) and high levels of SPIB (p = 1.5 × 10−2) were linked with poor prognosis of colon cancer patients." (PMID 34841706, 2021). "In colon cancer specimens, a positive expression correlation was noted between SPI1 and HK2 (R = 0.1067, p < 1 × 10−4) or PGK (R = 0.4026, p < 1 × 10−4)." (PMID 34841706, 2021). "It has been reported that the identification of hexokinase 2 (HK2) as a direct target of miR-143, and show that reintroduction of miR-143 in the colon cancer cell line DLD-1 leads to decreased lactate secretion." (PMID 33430318, 2021). "XA inhibited HK2 and glycolysis through the suppression of EGFR–Akt signalling colon cancer cell lines (HCT116, HT29, SW620) in vitro and in a murine xenograft model in vivo." (PMID 32843908, 2020). "Here, we reported the identification of HK2 as a target of miR-143, confirming the down-regulation of HK2 upon miR-143 overexpression of transcript cells as well as protein level in both DLD-1 and HCT116 colon cancer cell lines." (PMID 22691140, 2012). "Matrine could drastically decreased HIF-1α and its downstream regulatory targets of glucose metabolism such as GLUT1, HK2 and LDHA in HCT116 and SW620 colon cancer cells, thus reversing the Warburg Effect." (PMID 36339566, 2022). "Phosphorylation of the glycolysis enzyme hexokinase 2 (HK2) by Akt results in increased proliferation, tumorigenesis, and metastasis of colon cancer mediated by NF-κB and hypoxia inducible factor 1α (HIF-1 α) both in vitro and in vivo in mouse xenograft tumors." (PMID 35780223, 2022). "Moreover, in vitro and in vivo investigations on colon cancer showed that wogonin inhibited HIF-1α, HK2, PDK1, and LDHA expression." (PMID 36339566, 2022). "Given that DANCR and miR-125b-5p/HK2 inversely regulate cisplatin sensitivity of colon cancer, we examined whether DANCR influenced cisplatin resistance through suppressing the miR-125b-5p/HK2 axis." (PMID 32766131, 2020). "Similarly, GEPIA database also revealed that HIF1A expression positively correlated with HK2 and LDHA in colon cancer, rectal cancer and CRC, respectively." (PMID 33218358, 2020).
colon carcinoma (continued). "As HK2 is the key enzyme that determines the direction and magnitude of glucose flux, our study identified PHLPP as a novel regulator of glucose metabolism by controlling HK2 activity in colon cancer cells." (PMID 28179998, 2017). "We found that POU2F1 transcripts were positively correlated with hexokinase 2 (HK2), 6-phosphofructo-2-kinase/fructose-2,6-biphosphatase 2 (PFKFB2), ALDOA, pyruvate kinase M1/2 (PKM), lactate dehydrogenase A (LDHA), G6PD, and ribose 5-phosphate isomerase A (RPIA) levels in the colon cancer tissues." (PMID 34997215, 2022).
pancreatic cancer (45 papers, 2012 to 2025). "More importantly, MIR210HG knockdown inhibited pancreatic cancer cell glycolysis by regulating the expression of glycolysis-associated HK2 and pyruvate kinase muscle isoform M2 (PKM2)." (PMID 40630951, 2025). "Benitrobenrazide, an innovative selective HK2 inhibitor, demonstrates the capability to target the binding site and preclude glucose association with HK2, thus efficaciously inhibiting pancreatic cancer growth by disrupting glycolytic pathways." (PMID 38034101, 2023). "By gain-of-function and loss-of-function experiments, we found miR-202 impaired pancreatic cancer glycolysis and subsequently repressed cell proliferation by directly targeting hexokinase 2 (HK2)." (PMID 33442412, 2021). "The high expression of hexokinase 2 (HK2) was also found to be associated with gemcitabine resistance to pancreatic cancer, which is the core enzyme to regulate glycolysis by the first-step reaction." (PMID 32050640, 2020). "We found that HK2 was overexpressed in pancreatic cancer and associated with poor prognosis." (PMID 31426130, 2019). "Therefore, more studies designed rationally are required to confirm that elevated HK2 expression is associated with unfavorable outcome in patients with pancreatic cancer." (PMID 27824926, 2016). "However, polymorphisms in HK4 and HK2 affect the risk and clinical outcome in pancreatic cancer." (PMID 29504907, 2018). "MIR210HG affects pancreatic cancer cell phenotypes including proliferation, invasion, migration, and glycolysis by regulating the miR-125b-5p/HK2/PKM2 axis." (PMID 40630951, 2025). "This included GLUT1 and HK2, which have been previously shown to significantly increase aerobic glycolysis in pancreatic cancer and are induced by KRAS and STAT3, respectively." (PMID 40647442, 2025). "Pancreatic tumor cells specifically over-express glycolytic enzymes, such as hexokinase 2 (HK2), pyruvate dehydrogenase kinase isozyme 1 (PDK1) and lactate dehydrogenase A and B (LDHA, LDHB) compared to normal pancreatic cells." (PMID 36614196, 2023). "Mechanistically, BAG3 stabilizes hexokinase-2 mRNA which leads to increased hexokinase-2 (HK2) expression helping to promote aerobic glycolysis in pancreatic cancer cells, while BAG3 knockdown destabilizes HK2." (PMID 36980278, 2023). "HK2 knockdown increased the sensitivity of pancreatic cancer cell to GEM, the growth of xenograft tumor with HK2 knockdown was also further decreased with the GEM treatment compared with control in vivo." (PMID 31426130, 2019). "HK2 knockdown decreased pancreatic cancer cell proliferation, migration viability, and promoted cell apoptosis in vitro." (PMID 31426130, 2019). "To confirm the role of HK2 in pancreatic cancer cells, we analyzed HK2 expression in five pancreatic cancer cell lines via western blot analysis." (PMID 31426130, 2019). "Hexokinase 2 (HK2) overexpression promoted pancreatic cancer growth and gemcitabine (GEM) resistance." (PMID 31426130, 2019). "Given that HK2 promoted cell proliferation and resistance to apoptosis in pancreatic cancer cells, we analyzed the response to GEM therapy when HK2 was knocked down." (PMID 31426130, 2019). "From GSE287735, HK2 expression was also higher in pancreatic tumors than that in peritumor tissue (P < .05)." (PMID 31426130, 2019). "From GSE15471 with 39 pairs of pancreatic tumor and peritumor tissues, we found that HK2 expression was higher in pancreatic tumors compared with the corresponding peritumor tissue (P < .05)." (PMID 31426130, 2019). "To further explore HK2 expression in pancreatic cancer samples, we analyzed the pancreatic tumor TMA with 108 samples and found that HK2 was commonly expressed in the tumors." (PMID 31426130, 2019). "Overexpression of HK1 and HK2 genes was reported in many tumors including colorectal, prostate, breast, lung, gastrointestinal, and pancreatic cancers." (PMID 29504907, 2018).
pancreatic cancer (continued). "In pancreatic cancer, although the positive expression of HK2 exhibited borderline significant prognostic value for OS, the combination of elevated expression of HK2 and PKM2 was found to be significant (P<0.05)." (PMID 27824926, 2016). "And yet for all that, as a key regulator of glycolysis, the expression of HK2 is likely significant for the progression and prognosis of pancreatic cancer." (PMID 27824926, 2016). "Besides pancreatic cancer, a high level of HK2 was also related to the chemoresistance in epithelial ovarian cancer." (PMID 32050640, 2020). "HK2 high expression in pancreatic cancer showed GEM resistance." (PMID 31426130, 2019). "The results suggested that HK2 possibly played important roles in pancreatic cancer." (PMID 31426130, 2019). "The study described in this report established the critical role of HK2 overexpression in resistance to GEM‐induced cell apoptosis and elucidated the underlying mechanism in pancreatic cancer, which demonstrated that HK2 deletion increases sensitivity to GEM therapy." (PMID 31426130, 2019). "To establish the expression of HK2 in pancreatic cancer, we analyzed the GEO database." (PMID 31426130, 2019). "GEO database showed that HK2 was overexpressed in pancreatic cancer." (PMID 31426130, 2019). "Our exploration found that GEM could increase HK2 dimer in pancreatic cancer cells." (PMID 31426130, 2019). "In pancreatic cancer cells, ALDH1A3 increases the expression of HK2 by its activation of the PI3K/AKT/mTOR pathway." (PMID 39251846, 2024). "The HK2 inhibitor 2-DG impairs cell proliferation and viability, especially in combination with BAY-293 for all 3 pancreatic cancer cell lines tested." (PMID 36048281, 2022). "Consistent with this important role of glucose metabolism in pancreatic cancer growth, we identified GLUT1 and HK2 as two of the metabolic genes upregulated by apelin that were previously implicated in PDAC." (PMID 36142542, 2022). "Quinones: The expression of GLUT1, HK2, and PFK1 is suppressed and the level of HIF-1α is lowered by emodin and rhein in human pancreatic cancer cells (MiaPaCa2)." (PMID 36339566, 2022). "Further, it was connoted that CASC9, a hypoxia-inducible lncRNA, is regulated by HIF-1α and drives glycolysis via the upregulation of hexokinase 2 (HK2), lactate dehydrogenase A (LDHA), and glucose transporter type 4 (GLUT4) levels in pancreatic cancer." (PMID 34298879, 2021). "Herein, the overexpression of DLEU2L in pancreatic cancer cells successfully downregulated the expression of GLUT1, LDHB, HK2, and PKM2, which are positive regulators of the Warburg effect." (PMID 33968986, 2021). "However, it was unclear whether HK2 was responsible for GEM resistance in pancreatic cancer." (PMID 31426130, 2019). "In pancreatic cancer, KRAS upregulates GLUT1 (glucose transporter 1), as well as HK1 (hexokinase 1), HK2 (hexokinase 2), PFK1 (phosphofructokinase 1) and LDHA (lactate dehydrogenase A), which are key enzymes for the glycolytic processes." (PMID 31225458, 2018). "Comparing the expression levels between the tissue sections from multiple patients, all pancreatic tumor specimens stained positive for GLUT1, HK2, ENO3, LDHA and PKM2." (PMID 22412968, 2012). "Moreover, KRAS G12D extinction also downregulates several rate-limiting glycolytic enzymes like HK1, hexokinase 2 (HK2), PFKl and lactate dehydrogenase A (LDHA), while decreasing the glucose uptake and lactate production in pancreatic cancer." (PMID 39806421, 2025). "This could be illustrated by the induction of gene expression of HK2 and the silencing of GCK in liver and pancreatic cancers." (PMID 37109475, 2023). "There are several reports regarding the function of HK1, HK2, and GCK in pancreatic cancer." (PMID 36834681, 2023).
pancreatic cancer (continued). "Graviola, which is extracted from Annona Muricata, could inhibit glucose uptake in pancreatic cancer cells by suppressing the expression of HIF-1α, NF-κB, GLUT1/GLUT4, HK2 and LDHA according to a recent study, thereby decrease ATP generation." (PMID 36339566, 2022). "Emodin and rhein are anthraquinone components derived from Rheum palmatum that can inhibit HIF-1α and diminish the downstream glucose regulating molecules, GLUT1, as well as reduce the expression of HK2 and PFK1 and prevent the Warburg Effect of human pancreatic cancer cells." (PMID 36339566, 2022). "For example, a new study reported that hyperglycemia could enhance glycolysis by increasing LDHA activity and HK2, PFKP expression to promote pancreatic cancer progression." (PMID 31889896, 2019). "Finally, we analyzed the expressional correlation of EGLN2 with GLUT1, HK2, and LDHA in TCGA pancreatic cancer patients." (PMID 29476053, 2018). "However, inconsistent with our in vitro observations, EGLN2 negatively and significantly correlated with HK2 and LDHA expression in pancreatic cancer patients." (PMID 29476053, 2018). "GEM‐resistant pancreatic cancer showed the increase of HK2 dimer rather than HK2 mRNA or protein." (PMID 31426130, 2019). "Interestingly, we also found HK2 failed to predict the outcome of patients with pancreatic cancer." (PMID 27824926, 2016).
melanoma (44 papers, 2014 to 2025). A malignant, usually aggressive tumor composed of atypical, neoplastic melanocytes. "A key glycolytic enzyme, hexokinase 2 (HK2) is associated with metabolic reprogramming in melanoma cells." (PMID 40191195, 2025). "Specifically, we genetically enforced the expression of hexokinase 2 (HK2) in melanoma specific T-cells which led to an augmented glycolytic, oxygen consumption rates, and ATP production in T cells." (PMID 40181966, 2025). "Collectively, our findings suggest that the oncogenic functions of HK2 in melanoma cells are, at least in part, dependent on the translational regulation of the SOX10 mRNA via its 5′UTR." (PMID 40956859, 2025). "Accordingly, we found that HK2 depletion decreases colony formation of melanoma cells (A375 and A2058) after 10 days of culture." (PMID 40956859, 2025). "Here, we describe a novel extra-glycolytic function of HK2 in melanoma cell lines chosen due to the critical role of glycolysis and OXPHOS in melanoma development." (PMID 40956859, 2025). "Taken together, these results indicate that HK2 directly interacts with RNA in living melanoma cells." (PMID 40956859, 2025). "Ectopic expression of Myc-DDK-SOX10 (ΔUTR), however, reduces the effect of HK2 depletion, suggesting that the effect observed on colony formation of melanoma cells requires, in part, the SOX10 UTR." (PMID 40956859, 2025). "We further showed that HK2-dependent SOX10 mRNA translation is involved in melanoma cell proliferation and colony formation." (PMID 40956859, 2025). "The CCK‐8 assay revealed that restrained melanoma cell viability due to sh‐SPI1 transfection was abrogated by HK2 overexpression." (PMID 37539493, 2023). "In conclusion, kaempferol inhibited melanoma metastasis through stopping the aerobic glycolysis of melanoma cells, in which the binding of HK2 as well as VDAC1 on mitochondria was broken." (PMID 37239974, 2023). "The findings in our study suggested that SPI1 interacted with HK2 and positively regulated its expression to promote melanoma progression." (PMID 37539493, 2023). "In general, our work indicated that the transcription factor SPI1 promoted melanoma cell proliferation, metastasis and glycolysis by promoting HK2 expression and activating the AKT1/mTOR signalling pathway." (PMID 37539493, 2023). "Altogether, our work elucidated that downregulation of SPI1 hampered cell proliferation, metastasis and glycolysis in melanoma cells by blocking the AKT1/mTOR axis by targeting HK2." (PMID 37539493, 2023). "qRT–PCR analysis indicated that HK2 transcription in melanoma tissues was dramatically elevated compared with that in adjacent normal tissues." (PMID 37539493, 2023). "LncRNA RNCR2 promoted glycolysis and EMT and proliferation of melanoma cells via interacting with miR-495-3p and upregulating HK2 in melanoma." (PMID 36313695, 2022). "Another miR affecting melanoma glycolysis is miR-216a-5p, which inhibits hexokinase 2 (HK2)—an enzyme initiating glycolysis." (PMID 33918883, 2021). "Western blot analysis of whole cell lysates confirmed the observed reduction in c‐MYC, GLUT1 and HK2 in sensitive melanoma cells." (PMID 31833658, 2020). "To investigate whether HK2 is involved in the translational regulation of specific mRNAs, we depleted (siRNA) HK2 in A375 melanoma cells." (PMID 40956859, 2025). "Indeed, Myc-DDK-SOX10 (ΔUTR) ectopic expression reduced the effect of HK2 depletion on colony formation, while rescuing the proliferation properties of the melanoma cells." (PMID 40956859, 2025). "However, HK2 depletion affects melanoma cell migration via other mechanisms, independently of SOX10." (PMID 40956859, 2025). "We found that HK2 specifically regulates translation of the mRNA encoding SOX10, a transcription factor implicated in the regulation of tumor initiation, maintenance, and progression in melanoma." (PMID 40956859, 2025).